MTOR (mechanistic target of rapamycin kinase)
Diseases named in the same sentence as MTOR in open-access papers (continued):
Sharing a sentence is not in itself a finding about the gene and the disease.
Hepatic steatosis (continued). "This is consistent with previous reports that BBR can led to high autophagy flux by inhibition of the ERK1/2-dependent mTOR pathway in hepatic steatosis." (PMID 34422209, 2021). "RAPA administration exhibited significantly improved insulin resistance and hepatic steatosis in type 2 diabetes (T2DM) through inhibition of mTOR and alleviation of disorders of lipid metabolism." (PMID 32548088, 2020). "Other than interaction with the autophagy pathway, the mTOR pathway also contributed to alcohol-induced liver steatosis and injury by regulating lipogenesis." (PMID 31614437, 2019). "Taken together, our results indicated that activation of AMPK/mTOR-dependent autophagy pathway plays an important role in PCW-mediated protection of hepatic steatosis." (PMID 31569635, 2019). "Unexpectedly, hepAGT+/+ mice receiving losartan (10 mg/kg/day) displayed similar body weight gain, fat mass, and liver steatosis severity, as well as the abundance of p-Akt and p-mTOR compared with the mice treated with vehicle." (PMID 31604805, 2019). "Future studies are required that should focus on the link of miR-29a with mTOR pathway can therefore reflect the changes in gain of miR-29a reversed MCD diet hepatic steatosis." (PMID 30917489, 2019). "Collectively, our results indicate that dysregulation of the hepatic mTOR pathway is involved in hepatic steatosis and HCC." (PMID 31409773, 2019). "In the present investigation, we assessed the functional contribution of SCD1 in vivo both on hepatic steatosis driven by AKT/mTOR and liver cancer development induced by AKT/Ras co-expression." (PMID 24069385, 2013). "While in the liver, the formation of the β-catenin/mTOR complex could lead to the upregulation of lipid synthesis-related gene, promoting lipogenesis and resulting in hepatic steatosis." (PMID 39905294, 2025). "MYCBP2 inhibits signaling pathways that drive hepatic steatosis, including mTOR and p38 MAPK, while also suppressing adipogenesis by promoting SMAD4 ubiquitination, possibly explaining why aggregated deleterious variants in MYCBP2 were positively associated with both MASLD and body fat percentage." (PMID 40065360, 2025). "Ethanol intake contributes to hepatic steatosis through several inter-related mechanisms, including suppression of fatty acid oxidation with simultaneous exacerbation of lipogenesis, which has been associated with defective PI3K/Akt/mTOR signalling." (PMID 41032702, 2025). "Moreover, L-Phe regulates the BNIP3-mediated PPARα and AMPK/mTOR signalling pathways to promote hepatic steatosis." (PMID 40588730, 2025). "In addition, AMPK can inhibit the downstream targets such as sterol regulatory element-binding protein-1c (SREBP-1c) and rapamycin target (mTOR), reduce lipid synthesis, promote autophagy and β-oxidation, and reduce hepatic steatosis in MAFLD." (PMID 41573724, 2025). "Compared with untreated Ufbp1Δ/Δhep mice, the liver samples from rapamycin administered Ufbp1Δ/Δhep mice exhibited attenuated hepatic steatosis, as well as decreased cytoplasmic vacuolation, inflammatory cell infiltration, and phosphorylation levels of mTOR, p70S6, 4EBP-1, and GβL." (PMID 37131258, 2023). "Activated AMPK can negatively modulate mTOR, which is a key modulator in the process of autophagy induction, consequently upregulated the autophagy levels in oceans of cells and diseases, such as tumor, hepatic steatosis, and COPD." (PMID 34765000, 2021). "Dysregulation of the mTOR pathway—a key controller of lipid metabolism, regulating lipogenesis in the liver, lipolysis in white adipose tissue, and adipogenesis—may promote liver steatosis and development of NAFLD." (PMID 32069846, 2020). "Secondary biliary acids produced by the metabolic activity of the gut microbiota are also able to enhance AKT-independent mTOR activity in the liver to promote hepatic steatosis and HCC, while depleting gut microbiota with antibiotics reverses these mechanisms." (PMID 32070029, 2020).
Hepatic steatosis (continued). "An immunosuppressive drug rapamycin, one of mechanistic/mammalian target of rapamycin (mTOR) inhibitors, has been shown to prevent the development of hepatic steatosis, suggesting that mTOR could influence the pathology of MAFLD by regulating the inflammatory response." (PMID 36982539, 2023). "Herein, MG increased ATG5-12, ATG7, Beclin1, ULK1, and LC3-II/I ratio and decreased p62/SQSTM1 and p-mTOR in the liver of Tylo-injected rats and PA-stimulated HepG2 cells, suggesting that MG might promote the formation of autophagic flux to alleviate hepatic steatosis." (PMID 32992548, 2020). "Previous animal and cell culture studies implicated mammalian target of rapamycin (mTOR), signal transducer and activator of transcription-3 (STAT3), extracellular signal-regulated kinase (ERK) and estrogen-receptor α in the pathogenesis of hepatic steatosis and disease progression." (PMID 29615085, 2018). "The dysregulation of mTOR promotes hepatic steatosis through SREBP-mediated lipogenesis, while liver-specific PPDPF deletion induces spontaneous fatty liver by negatively regulating the mTORC1-S6K-SREBP1 signaling pathway." (PMID 40868109, 2025). "mTOR inhibitors (e.g., everolimus) inhibit hepatic lipid metabolism genes (e.g., PPARα, AMPK), exacerbating hepatic steatosis in T2DM patients." (PMID 40963676, 2025). "Combined polyphenol treatment significantly improved hepatic steatosis and modulated the PI3K/AKT/mTOR and HIF-1 signaling pathways, restoring the expression of related target genes and proteins, including PI3K, mTOR, STAT3, HIF-1α, and VEGF." (PMID 41011683, 2025). "Compounds like magnolol (MG), in HepG2 and Wistar rat models, demonstrate therapeutic potential by inhibiting mTOR and activating the Nrf2-ARE pathway, enhancing autophagic flux and reversing hepatic steatosis." (PMID 39175576, 2024). "In another study, ncRNA miR-122-5p was found to attenuate inflammatory response and oxidative stress damage in dietary-induced NAFLD possibly via the upregulation of mTOR downstream FOXO3 in palmitic acid (PA)-treated L02 cells and HFD-induced fatty liver." (PMID 37760534, 2023). "A recent paper discovered a new pathway linking PLIN3 and mTOR, in which PLIN3 was essential to activate lipophagy and protect against fatty liver worsening to steatohepatitis." (PMID 36364243, 2022). "Nevertheless, pharmaceutical enhancement of autophagy by rapamycin or carbamazepine which inhibits mTOR reduced hepatic steatosis in NASH model, and severe hepatic steatosis occurs in mice with hepatic deletion of Atg5." (PMID 36009582, 2022). "It has been shown that eugenol activates AMPK phosphorylation, but suppresses mTOR and P70S6K phosphorylation, which attenuates hepatic steatosis and fibrosis." (PMID 32153404, 2020). "Mechanistically, we found that H19 promoted hepatic steatosis by up‐regulating and the mTORC1 signalling axis (including active RAPTOR, mTOR, S6K SREBP and suppress LIPIN1) and MLXIPL transcriptional network in hepatocytes." (PMID 31809000, 2020). "We examined the expression patterns of mTOR, STAT3, ERK and estrogen-receptor α in liver tissues from patients diagnosed with hepatic steatosis." (PMID 29615085, 2018). "mTOR, phosphorylated STAT3, phosphorylated pERK, estrogen-receptor α were found to be more frequently expressed in the hepatic steatosis group than in the control group." (PMID 29615085, 2018). "Using the previous fatty liver model, it was further revealed that HFD induction in KO control mice led to mTOR signaling pathway activation in the liver, as evidenced by increased levels of p-mTOR, GβL, p-p70S6, and p-4EBP-1." (PMID 37131258, 2023). "Furthermore, irbesartan can ameliorate hyperlipidemia and liver steatosis by upregulating the expression of PPAR-γ, activating the AMP-activated protein kinase/protein kinase B/mTOR signaling pathway and inducing liver autophagy." (PMID 35135573, 2022).
Hepatic steatosis (continued). "In addition, the anti-hepatic steatosis effects of LEP are accompanied by suppression of ER stress-mediated autophagy, including the MAPK and PI3K/AKT/mTOR signaling pathways." (PMID 32521713, 2020). "Administration of losartan did not affect diet-induced body weight gain, liver steatosis severity, and hepatic p-Akt, p-mTOR, and SREBP1 protein abundance in hepAGT+/+ mice." (PMID 31604805, 2019). "We observed non-specific cytoplasmic or membranous staining of mTOR in non-neoplastic hepatocytes in all hepatic steatosis and control cases." (PMID 29615085, 2018). "The mammalian target of rapamycin (mTOR) controls lipid biosynthesis via various effector molecules, such as sterol regulatory element-binding protein like-1c (SREBP-1c) which engages in the development of hepatic steatosis." (PMID 29615085, 2018). "Our results indicate that SCD1 is not essential for AKT/mTOR-dependent hepatic steatosis and AKT/Ras-induced hepatocarcinogenesis in mice." (PMID 24069385, 2013). "MTOR inhibition reduces hepatic steatosis, indicating that high-protein diets may not reduce intrahepatic fat content through mTOR." (PMID 39958775, 2023). "However, from the results of increased ratio of LC3B II/LC3B I and decreased mTOR levels in this study, of which the former proves positive regulate factor of autophagy and the latter is negative, autophagy seems not contribute to olanzapine-induced hepatic steatosis." (PMID 35379885, 2022).
subependymal giant cell astrocytoma (93 papers, 2011 to 2025). A benign, slowly growing tumor (WHO grade I) typically arising in the wall of the lateral ventricles and composed of large ganglioid astrocytes. "The function loss of the TSC2 gene leads to aberrant mTOR pathway activation and multiple tumors including subependymal giant cell astrocytomas, angiomyolipomas, lymphangioleiomyomatosis, and angiofibromas." (PMID 37152430, 2023). "Everolimus is the first mTOR inhibitor approved as a treatment option in the USA and in Europe for patients with subependymal giant-cell astrocytomas (SEGAs) associated with TSC." (PMID 23730262, 2012). "mTOR activation has been associated with subependymal giant cell astrocytoma (SEGA) which occurs in up to 15% of TSC patients." (PMID 27926496, 2017). "For example, for subependymal giant cell astrocytoma (SEGA) associated with the tumor predisposition syndrome tuberous sclerosis, the mTOR inhibitor everolimus is now FDA-approved in the upfront setting based on a landmark phase 3 clinical trial showing its efficacy." (PMID 40094009, 2025). "A couple of studies have demonstrated an increased expression of phospho-ERK 1⁄2, mitogen-activated protein kinase (MAPK), phospho-Akt, and phospho-mTor in a small group of canine astrocytomas." (PMID 39061577, 2024). "Of note, mTOR inhibitors have been US FDA-approved for the treatment of several TSC-associated lesions, such as subependymal giant cell astrocytoma, kidney angiolipoma, lung lymphangioleiomyomatosis, and skin angiofibroma." (PMID 37648887, 2023). "eIF signalling is regulated upstream via the PI3K/AKT/mTOR pathway which has previously been demonstrated to be increasingly activated and dysregulated in astrocytomas (WHO grade I-IV)." (PMID 37907716, 2023). "For subependymal giant cell astrocytomas (SEGAs), mammalian target of rapamycin (mTOR) inhibitors (everolimus or sirolimus) can be given following maximal safe resection or in the context of recurrent disease." (PMID 36249063, 2022). "Everolimus is an inhibitor of mammalian target of rapamycin (mTOR), a serine-threonine kinase; it is indicated for use in children with subependymal giant cell astrocytoma." (PMID 36015138, 2022). "In the PNET dataset, 3.3% of cases harboured TSC1 or TSC2 mutations conferring sensitivity to the mammalian target of rapamycin (mTOR) inhibitor, everolimus, currently approved for renal angiomyolipomas and giant cell astrocytomas." (PMID 35849877, 2022). "The mammalian target of rapamycin (mTOR) inhibitor everolimus can restrict cell growth and proliferation and proved effective in reducing the volume of subependymal giant cell astrocytomas in a phase III trial." (PMID 34568049, 2021). "The mTOR inhibitor everolimus is approved by FDA for the treatment of subependymal giant cell astrocytomas, angiomyolipomas, and complex partial seizures in TSC patients." (PMID 34135323, 2021). "Since the first human studies of the mTOR inhibitor Rapamycin to treat astrocytomas in TSC, the mTOR inhibitor Everolimus has been licensed by the UK MHRA and US FDA to treat aspects of TSC, including refractory seizures." (PMID 32087199, 2020). "Early detection of giant cell astrocytoma often enables treatment with medical therapies such as mTOR inhibitors obviating the need for early neurosurgical interventions." (PMID 33409061, 2020). "Enhanced mTOR activity in TS often leads to cortical malformations during development, slow-growing astrocytomas, and cognitive deficits." (PMID 29789464, 2018). "Recent research has helped us understand the pathophysiology of TSC, which has led to the use of mTOR inhibitors for the treatment of certain manifestations of TSC including subependymal giant cell astrocytomas (SEGAs) and renal angiomyolipomas." (PMID 28057044, 2017). "The mTOR-Inhibitor Everolimus (Votubia®) was approved for the treatment of subependymal giant cell astrocytoma (SEGA) and renal angiomyolipoma (AML) in Europe in 2011." (PMID 27809914, 2016).
subependymal giant cell astrocytoma (continued). "The aim of the study was to evaluate the serum profiles of miRNAs in patients with TSC and subependymal giant cell astrocytoma (SEGA) treated with mTOR inhibitor (everolimus)." (PMID 27680012, 2016). "mTOR inhibitors have recently been found to be effective for subependymal giant cell astrocytoma, renal angiomyolipoma, and pulmonary lymphangioleiomyomatosis, which are severe manifestations of TSC." (PMID 25889454, 2015). "Clinical trials of mTOR inhibitors for treating AMLs, lymphangioleiomyomatosis, and subependymal giant cell astrocytomas are actively being undertaken." (PMID 24558502, 2014). "Subependymal giant cell astrocytoma (SEGA), another TSC associated neoplasm, can also be successfully managed by mTOR inhibition, and everolimus is already an FDA-approved drug for non-resectable SEGAs." (PMID 22943457, 2012). "It is worthy of note that 3 independent reports dealing with different grade of astrocytomas denoted a correlation of p-mTOR expression with tumor grade." (PMID 22530122, 2012). "Some reports have investigated the clinical and prognostic significance of activated mTOR (phosphorylated mTOR, p-mTOR) in human astrocytomas." (PMID 22530122, 2012). "Subependymal giant cell astrocytomas (SEGAs) are benign brain tumors associated with TSC that have traditionally been treated by surgery, but for which mTOR inhibitors have recently been suggested as potential alternative treatments." (PMID 21415462, 2011). "The main current clinical complication related to TSC for which treatment with mTOR inhibitors is indicated are subependymal giant cell astrocytomas (SEGA)." (PMID 21415462, 2011). "Recently, mTOR inhibitors (mTORi) such as sirolimus and everolimus have been shown to be effective in the treatment of the TSC-associated tumors in the brain (subependymal giant cell astrocytoma [SEGA]), kidney (angiomyolipoma [AML] and lymphangioleiomyomatosis), and cardiac rhabdomyoma." (PMID 38480570, 2024). "Interestingly, it has been seen that, when mTOR signaling suppression occurs, apoptosis is observed in tumor cells, and astrocytoma is transformed into oligodendroglioma." (PMID 39061577, 2024). "Subependymal giant cell astrocytomas are led by mTOR activation; mTORi are active drugs that may induce the regression of the tumor in children affected by these tumors." (PMID 37397394, 2023). "Within this study, the protein expression of PI3K/AKT/mTOR pathway members was analyzed and activation of this pathway in astrocytomas could be confirmed." (PMID 33807050, 2021). "Moreover, a recent study has demonstrated that combination of carboplatin with either everolimus (mTOR inhibitor) or trametinib (ERK inhibitor) decreased cellular proliferation of astrocytoma cells." (PMID 29642900, 2018). "Development of the mTOR inhibitors everolimus and sirolimus has led to considerable progress in the treatment of renal angiomyolipomata, pulmonary lymphangioleiomyomatosis, and subependymal giant cell astrocytomas in the brain." (PMID 28663780, 2017). "Several human studies provided strong evidence on the key role of an altered mTOR signaling pathway in low-grade astrocytoma, such as subependymal giant cell astrocytoma (SEGA), a rare, slow-growing benign tumor (WHO grade I) which mainly occurs in young patients." (PMID 29259984, 2017). "Also some clinical trials showed beneficial effect of mTOR inhibitors in lymphangioleiomyomatosis and astrocytomas." (PMID 23140536, 2012). "From a neuro-oncological perspective, LEATs and subependymal giant cell astrocytomas (SEGA) represent the best-known examples of pathological mTOR activation." (PMID 41074169, 2025).